LIMS2 (LIM zinc finger domain containing 2)
Description:
Adapter protein in a cytoplasmic complex linking beta-integrins to the actin cytoskeleton, bridges the complex to cell surface receptor tyrosine kinases and growth factor receptors. Plays a role in modulating cell spreading and migration.
Synonyms: PINCH-2; PINCH2; LGMD2W; MDRCMTT
Tractability: Antibody: UniProt places it where antibodies can reach, with high confidence; its Gene Ontology location is reachable by antibodies, with medium confidence. PROTAC: ubiquitination databases record sites on it.
Gene: Protein-coding gene on chromosome 2 (127,638,381 to 127,681,786, reverse strand). Ensembl gene ENSG00000072163.
Subcellular location: Nucleus; Cell junction, focal adhesion; Cell membrane
Subcellular location (Human Protein Atlas): Focal adhesion sites
Pathways (Reactome):
Cell-Cell communication: Cell-extracellular matrix interactions
Gene Ontology:
Biological process: cell-cell adhesion; cell-cell junction organization; positive regulation of integrin-mediated signaling pathway
Cellular component: focal adhesion; cell-cell junction; cytoplasm; cytosol; nucleus; plasma membrane
Genetic constraint (gnomAD): Loss-of-function variants: 31 observed, 42.46 expected, observed/expected ratio (o/e) 0.73, 90% interval 0.55 to 0.99. The upper end of that interval is the gene's LOEUF score, 0.99, which puts it in group 4 of 6, group 1 being the genes least tolerant of losing a copy. Missense variants: 485 observed, 462.07 expected, observed/expected ratio (o/e) 1.05, 90% interval 0.97 to 1.13. Synonymous variants: 173 observed, 180.3 expected, observed/expected ratio (o/e) 0.96, 90% interval 0.85 to 1.09.
Gene-disease validity (ClinGen):
ClinGen rates the evidence that LIMS2 causes each of these diseases.
autosomal recessive limb-girdle muscular dystrophy (autosomal recessive): Disputed. Autosomal recessive form of limb-girdle muscular dystrophy.
Homologues: Orthologues: chimpanzee LIMS2 (99% identical), macaque LIMS2 (99% identical), pig LIMS2 (96% identical), guinea pig LIMS2 (94% identical), mouse Lims2 (91% identical), rat Lims2 (91% identical), dog LIMS2 (75% identical), rabbit LIMS2 (75% identical), Drosophila melanogaster stck (63% identical), Caenorhabditis elegans unc-97 (59% identical), Caenorhabditis elegans pin-2 (34% identical), Drosophila melanogaster Zasp67 (22% identical). Paralogues in human: LIMS1 (82% identical), LIMS3 (79% identical), LIMS4 (79% identical).
Diseases named in the same sentence as LIMS2 in open-access papers:
LIMS2 is named in the same sentence as 23 diseases in open-access papers, as found by Europe PMC text mining. Sharing a sentence is not in itself a finding about the gene and the disease. The quoted sentences say what the papers report.
gastric cancer (3 papers, 2022 to 2025). A primary or metastatic malignant neoplasm involving the stomach. "The expression of LIMS2 was decreased in gastric cancer, which was significantly associated with the increased CpG island methylation." (PMID 36276291, 2022). "Epigenetic silencing of LIMS2 has been found in gastric cancer." (PMID 36212176, 2022). "Interestingly, we found that the methylation level at the promoter of LIMS2 gene was increased in OS cells compared with the normal osteoblast, which was consistent with the finding in gastric cancer." (PMID 36276291, 2022). "Moreover, the in vitro assay showed that LIMS2 overexpression inhibited the growth, migration, and invasion of OS cells, suggesting that LIMS2 functioned as a tumor suppressor in OS, which was similar as reported in gastric cancer and colon cancer." (PMID 36276291, 2022). "In addition, silencing of LIMS2 promoted the proliferation and migration of gastric cancer cells." (PMID 36276291, 2022).
cervical cancer (2 papers, 2022 to 2024). A primary or metastatic malignant neoplasm involving the cervix. "DNMT3A mediated the methylation of the CpG island at the promoter of LIMS2, and thus diminishing the expression of LIMS2 in cervical cancer cells." (PMID 39161894, 2024). "Extracellular vesicles secreted by mesenchymal stem cells inhibit the progression of cervical cancer by transferring the microRNA miR-331-3p, which reduces the level of methylation of LIMS2 in cancer cells." (PMID 36212176, 2022).
colon cancer (2 papers, 2017 to 2022). "LIMS2 expression was declined in colon cancer, and overexpression of LIMS2 significantly inhibited the migration of colon cancer cells." (PMID 36276291, 2022). "In addition, we also analyzed a pair of genes, LIMS2, down-regulated in colon cancer epithelial cells compared with normal epithelial colon cells, and MYH11 significantly up-regulated in colorectal tumor tissues compared with normal colon tissues." (PMID 28427173, 2017). "Moreover, LIMS2 expression was declined in colon cancer, and LIMS2 overexpression could inhibit the migration of colon cancer cells." (PMID 36276291, 2022).
melanoma (2 papers, 2019 to 2022). A malignant, usually aggressive tumor composed of atypical, neoplastic melanocytes. "In addition, LIMS2 was highly expressed in melanoma cells with heparinase gene silencing (HPSE), leading to cell apoptosis." (PMID 36276291, 2022). "Nevertheless, we were able to obtain reproducible up‐regulation of genes including EGR1, TXNIP, AXL, CYR61, LIMS2 and TNFRSF12A in MDA‐MB‐435s and MV3 melanoma cell lines and significant increase in protein levels as well, suggesting potential implication in other melanoma cells." (PMID 31044520, 2019).
bladder cancer (1 paper, 2025). "Notably, the MR results suggested a causal association between LIMS2 expression and bladder cancer risk." (PMID 40755754, 2025). "Finally, intersecting these key genes with risk-consistent genes yielded eight immune-related genes that were negatively associated with bladder cancer risk: LIMS2, TP53INP2, IRAK3, STX2, CYP27A1, IL11RA, KCNMB1, and PDLIM7." (PMID 40755754, 2025). "In vitro qRT-PCR validation in bladder cancer cell lines showed downregulation of LIMS2, IRAK3, STX2, IL11RA, KCNMB1, and PDLIM7, consistent with bioinformatics findings, suggesting that these genes may serve as potential therapeutic targets." (PMID 40755754, 2025). "The consistent downregulation of these genes in bladder cancer tissues was further validated using independent public datasets, and qRT-PCR experiments confirmed the differential expression of the following six genes: LIMS2, IRAK3, STX2, IL11RA, KCNMB1, and PDLIM7." (PMID 40755754, 2025). "Subsequent box plot analysis further demonstrated significantly lower expression of six genes (LIMS2, IRAK3, STX2, IL11RA, KCNMB1, and PDLIM7) in bladder cancer cell lines, consistent with bioinformatics analysis." (PMID 40755754, 2025). "Differential expression analysis revealed that, compared to the normal bladder cell line SV, the expression levels of LIMS2, IL11RA, KCNMB1, and PDLIM7 were significantly downregulated in all three bladder cancer cell lines (5637, T24, and HT1376)." (PMID 40755754, 2025). "Through integrated multi-omics analysis and experimental validation, six genes, LIMS2, IRAK3, STX2, IL11RA, KCNMB1, and PDLIM7, were selected as potential immune-related biomarkers for bladder cancer, providing promising biomarkers and therapeutic targets for personalized treatment." (PMID 40755754, 2025).
bladder tumors (1 paper, 2025). "Combined with the immune infiltration analysis showing a significant positive correlation between LIMS2 and CD8+ T cell infiltration, this indicates that LIMS2 may regulate the immune microenvironment of bladder tumors." (PMID 40755754, 2025).
calpainopathies (1 paper, 2020). "While transient or persistent calf hypertrophy has been documented in calpainopathies, it is also a feature of the LIMS2-patients." (PMID 33250842, 2020).
malignant mesothelioma (1 paper, 2022). A malignant neoplasm of the pleura or peritoneum, arising from mesothelial cells. "However, LIMS2 mRNA level was increased in malignant mesothelioma compared with carcinomas involving serosal cavities, with its function in the progression of malignant mesothelioma remaining unknown." (PMID 36276291, 2022).
ovarian carcinoma (1 paper, 2025). A malignant neoplasm originating from the surface ovarian epithelium. "Although there are currently no clinical trials directly targeting LIMS2, its binding partner ILK has been identified as a potential therapeutic target in ovarian cancer." (PMID 40755754, 2025).
sarcoma (1 paper, 2022). A usually aggressive malignant neoplasm of the soft tissue or bone. "In addition, the promoter methylation level of LIMS2 was significantly increased in sarcoma compared to normal group, as shown in the UALCAN database." (PMID 36276291, 2022).
Sepsis (1 paper, 2025). Sepsis is defined as life-threatening organ dysfunction caused by a dysregulated host response to infection. "In rAAV-sh-controls, sepsis induced upregulation across TA and EDL muscle of Ilk1 and Fermt2 and integrin-receptor-complex-related genes Itga7, ItgB1, Tln1, Lims1, Lims2, Parva (P < 0.001), whereas in SOL muscle Lims1, Lims2 and Fermt2 were not and Vcl1 (P < 0.001) was upregulated." (PMID 41385533, 2025).
cancer (8 papers, 2020 to 2025). A tumor composed of atypical neoplastic, often pleomorphic cells that invade other tissues. "Currently, evidence has demonstrated that LIMS2 is implicated in the carcinogenesis of several kinds of cancers." (PMID 36276291, 2022). "Since LIMS2 encodes a protein involved in cell adhesion and cytoskeletal pathways, this hypomethylation may potentially increase cell motility and invasion - key hallmarks of cancer metastasis." (PMID 40791616, 2025). "It has been found that LIMS2 is involved in cell migration and adhesion via integrins and its deletion or downregulation correlated with promoting invasion and metastasis in several cancer types." (PMID 40137900, 2025). "Like LIMS1, studies have shown that LIMS2 takes part in cancer migration and invasion." (PMID 36276291, 2022). "Here, we first explored LIMS2 effect on the activation of MAPK signaling in cancer cells, and our results demonstrated that overexpression of LIMS2 could significantly inhibit the activation of MAPK signaling." (PMID 36276291, 2022). "Our study suggests that the regulatory changes for ABCC5 and LIMS2 led to the correlation of these two genes only existed in LUAD, which could be associated with LUAD cancer etiology." (PMID 35524179, 2022). "However, the role of LIMS2 in the progression of other types of cancers, such as OS remains unknown." (PMID 36276291, 2022). "Both ILVBL and ABCC5 genes did not form any edges in GTEx normal condition, which indicated that gaining the (ILVBL, LIMS2), (ILVBL, LIMS2), and (LIMS2, ABCC5) edges could be related to the formation of LUAD cancer." (PMID 35524179, 2022). "Only SLC7A11, TFAP2A, and LIMS2 are commonly regulated by the MDF in carcinomas (not in GBM), but only if the direction of the correlation was inversed for PAAC, whose impact on OS was also inverse." (PMID 32806596, 2020).
tumor (6 papers, 2017 to 2025). "The data showed that the expression levels of these proteins in tumor tissues were higher than those in normal tissues, except for the LIMS2 protein, which was consistent with mRNA expression." (PMID 36110210, 2022). "Furthermore, analysis of the GSE13507 dataset revealed that six genes, LIMS2, IRAK3, STX2, CYP27A1, IL11RA, and KCNMB1, had AUC values greater than 0.7, demonstrating good diagnostic potential in differentiating healthy adjacent tissues from tumor samples." (PMID 40755754, 2025). "To validate the expression levels of the eight key genes (LIMS2, TP53INP2, IRAK3, STX2, CYP27A1, IL11RA, KCNMB1, and PDLIM7) in tumor and non-tumor samples, we analyzed their expression in TCGA and GSE7476 datasets." (PMID 40755754, 2025). "Furthermore, qRT-PCR experiments showed that LIMS2, IRAK3, STX2, IL11RA, KCNMB1, and PDLM7 were significantly downregulated in the tumor group, consistent with the bioinformatic analysis results, suggesting their potential clinical value." (PMID 40755754, 2025). "Although its role in BC is not well characterized, the function of LIMS2 suggests its dysregulation could contribute to tumor progression." (PMID 40791616, 2025).
LIMS2 also shares sentences with these, for which no sentence is quoted: colorectal tumor (1 paper); dementia (1); gastric tumors (1); hepatocellular carcinoma (1); idiopathic pulmonary fibrosis (1); liver cancer (1); osteosarcoma (1); Parkinson’s (1); spina bifida (1); Stroke (1).